DOK3 (docking protein 3)
Description:
DOK proteins are enzymatically inert adaptor or scaffolding proteins. They provide a docking platform for the assembly of multimolecular signaling complexes. DOK3 is a negative regulator of JNK signaling in B-cells through interaction with INPP5D/SHIP1. May modulate ABL1 function (By similarity).
Synonyms: FLJ22570; DOKL
Tractability: Antibody: its Gene Ontology location is reachable by antibodies, with high confidence; UniProt places it where antibodies can reach, with medium confidence; the Human Protein Atlas places it where antibodies can reach. PROTAC: its protein half-life has been measured.
Gene: Protein-coding gene on chromosome 5 (177,501,904 to 177,511,274, reverse strand). Ensembl gene ENSG00000146094.
Subcellular location: Cytoplasm; Cell membrane
Subcellular location (Human Protein Atlas): Plasma membrane; Cytokinetic bridge; Cytosol; Nucleoplasm
Pathways (Reactome):
Immune System: Neutrophil degranulation
Gene Ontology:
Molecular function: protein binding; signaling adaptor activity
Biological process: Ras protein signal transduction
Cellular component: plasma membrane; ficolin-1-rich granule membrane; secretory granule membrane; cytoplasm
Genetic constraint (gnomAD): Loss-of-function variants: 25 observed, 23.74 expected, observed/expected ratio (o/e) 1.05, 90% interval 0.77 to 1.47. The upper end of that interval is the gene's LOEUF score, 1.47, which puts it in group 6 of 6, group 1 being the genes least tolerant of losing a copy. Missense variants: 619 observed, 558.23 expected, observed/expected ratio (o/e) 1.11, 90% interval 1.04 to 1.18. Synonymous variants: 266 observed, 240.53 expected, observed/expected ratio (o/e) 1.11, 90% interval 1 to 1.22.
Homologues: Orthologues: chimpanzee DOK3 (99% identical), macaque DOK3 (92% identical), dog DOK3 (81% identical), mouse Dok3 (78% identical), rabbit DOK3 (78% identical), rat Dok3 (78% identical), guinea pig DOK3 (77% identical), pig DOK3 (72% identical), Drosophila melanogaster Dok (21% identical), Caenorhabditis elegans rog-1 (15% identical), Drosophila melanogaster CG13398 (15% identical). Paralogues in human: DOK1 (31% identical), DOK2 (30% identical), DOK4 (15% identical), DOK5 (15% identical), DOK6 (15% identical), FRS2 (14% identical), FRS3 (13% identical).
Diseases named in the same sentence as DOK3 in open-access papers:
DOK3 is named in the same sentence as 44 diseases in open-access papers, as found by Europe PMC text mining. Sharing a sentence is not in itself a finding about the gene and the disease. The quoted sentences say what the papers report.
lung carcinoma (5 papers, 2017 to 2024). "However, there was a significant correlation between the prolongation of PFS following gefitinib treatment and plasma exosomal Docking Protein 3 (DOK3), a molecule implicated in B‐cell receptor signaling in lung cancer." (PMID 39611045, 2024). "There was also a significant reduction of DOK3 in lung cancer and aggressive histiocytic sarcoma." (PMID 33552156, 2021). "We identified seven proteins (Amph, Dok3, Ddx17, Mbip, Rim2, Skap2, TACC3, and Usp33) that are predicted to be EGFR interaction partners and/or share interaction partners within the EGFR pathway, and three of these (Amph, Rim2, and TACC3) show increased expression levels in lung cancer." (PMID 27956147, 2017).
histiocytic sarcoma (4 papers, 2012 to 2021). An aggressive malignant neoplasm with a poor response to therapy, usually presenting as stage III/IV disease. "A recent report showed that mice with coincident loss of Dok-1, Dok-2 and Dok-3 genes develop highly invasive and transplantable histiocytic sarcoma endogenously, and Dok-1/2/3−/− macrophages demonstrate enhanced proliferation ability, suggesting origination of the disease in monocytic cells." (PMID 22952867, 2012). "In addition, mice with combined knockouts of Dok1, Dok2, and Dok3 developed aggressive histiocytic sarcoma or lung adenocarcinoma." (PMID 24523872, 2014).
fungal infection (2 papers, 2020 to 2023). "For instance, association between Dok-3 and Card9 is pivotal for suppressing Card9 signaling and hence restraining the fungicidal properties of neutrophils such as phagocytosis, pro-inflammatory cytokines release and NETs formation during fungal infection." (PMID 33133079, 2020). "Upon fungal infection, the tyrosine residues on Dok-3 are phosphorylated and Dok-3 is gradually degraded." (PMID 33133079, 2020). "Since Dok3 suppresses Card9 activity, disrupting the Dok3–Card9 interaction could potentially be a novel therapeutic strategy used to boost neutrophilic responses to fight fungal infection." (PMID 37513967, 2023). "As such, we hypothesized that targeting the Dok3–Card9 interaction could represent a potential strategy to boost neutrophilic effector functions to fight fungal infection." (PMID 37513967, 2023). "Collectively, these data provide a proof of concept that disrupting the Dok3–Card9 interaction can boost the antifungal effector functions of neutrophils; they further suggest the potential utility of these peptide inhibitors as an immune-based therapeutic to fight fungal infection." (PMID 37513967, 2023).
glioblastoma (2 papers, 2024 to 2026). The most malignant astrocytic tumor (WHO grade IV). "Meta-analysis of multiple datasets confirmed that DOK3 is a significant risk factor for glioblastoma survival (HR > 1), with moderate heterogeneity across studies." (PMID 39726593, 2024). "In this study, we evaluated the effects of LPS treatment and DOK3 overexpression (OE) on U251MG glioblastoma cells, focusing on inflammatory cytokine expression, oxidative stress markers, and tumor-related processes." (PMID 39726593, 2024). "Validation of critical DEGs was performed through pan-cancer analysis and experimental studies, focusing on the role of DOK3 in modulating inflammation and oxidative stress in U251MG glioblastoma and BV2 microglia cells." (PMID 39726593, 2024). "In this study, we investigated the role of DOK3 and PAPOLA in tumor prognosis using U251MG glioblastoma cells." (PMID 39726593, 2024).
glioma (2 papers, 2024 to 2026). A benign or malignant brain and spinal cord tumor that arises from glial cells (astrocytes, oligodendrocytes, ependymal cells). "The roles of DOK3 and PAPOLA as central players in multiple diseases, including glioma, are further supported by existing research." (PMID 39726593, 2024).
lung adenocarcinoma (2 papers, 2014 to 2020). A carcinoma that arises from the lung and is characterized by the presence of malignant glandular epithelial cells. "Notably, mice deficient in Dok-3 were found to develop lung adenocarcinoma, and the effect was more pronounced in mice with compound ablation of Dok-1, -2, and -3, further demonstrating the overlapping and redundancies in function of the family of Dok proteins." (PMID 33133079, 2020).
Sepsis (2 papers, 2012 to 2021). Sepsis is defined as life-threatening organ dysfunction caused by a dysregulated host response to infection. "Thus, DOK3 plays a role both in vitro and in vivo limiting LPS-induced cytokine responses and sepsis." (PMID 22761938, 2012).
Alzheimer disease (1 paper, 2024). A progressive, neurodegenerative disease characterized by loss of function and death of nerve cells in several areas of the brain leading to loss of cognitive function such as memory and language. "A microarray gene expression profiling study found that DOK3 is upregulated in Alzheimer’s disease." (PMID 39726593, 2024).
asthma (1 paper, 2020). "A previous study showed the anti-inflammatory roles of Dok adaptors in chronic inflammatory diseases where DOK3 deficiency induces increase of TH2 cytokines in the asthma model mice; our results suggest a potential anti-inflammatory role of DOK3 in the colonic mucosa in UC." (PMID 32410873, 2020).
atopic dermatitis (1 paper, 2024). "Thus, the researchers demonstrated, in an experimental model, that the strength of the interaction of DOK3 with CARD11 may predispose one to the development of atopic dermatitis." (PMID 38672221, 2024). "DOK3 promotes atopic dermatitis by enabling phosphatase PP4C to inhibit the T-cell-signaling mediator CARD11." (PMID 38672221, 2024).
cognitive decline (1 paper, 2024). "Emerging evidence suggests that after an aSAH, DOK3 may contribute to cognitive decline or dementia by influencing apoptotic pathways and modulating immune cell trafficking." (PMID 39726593, 2024).
colitis (1 paper, 2021). Inflammation of the colon. "This suggests that the enhanced susceptibility to colitis in Dok3−/− mice can be reversed by the transfer of normal microbiota in a co-housing setting." (PMID 34743196, 2021). "In agreement with the co-housing study, Dok3+/+ and Dok3−/− littermates which harbor similar intestinal flora show comparable colitis susceptibility, which was less severe than that seen in Dok3−/− mice." (PMID 34743196, 2021). "To demonstrate that the dysbiotic microbiome of Dok3−/− mice contributes to their colitis susceptibility, we co-housed WT and Dok3−/− mice to allow for the exchange of microbiota through coprophagia." (PMID 34743196, 2021). "We observed that delivery of RAGE antagonist is able to attenuate the colitis susceptibility of Dok3−/− mice." (PMID 34743196, 2021). "On the other hand, treatment with antibiotics is able to completely rescue the colitis susceptibility of Dok3−/− mice, suggesting that altered gut microbiota is responsible for the exacerbated colitis in Dok3−/− mice." (PMID 34743196, 2021). "Dok3−/− mice treated with fluconazole showed comparable disease susceptibility as untreated Dok3−/− mice upon colitis induction, suggesting that gut fungi do not contribute to increased colonic inflammation in Dok3−/− mice during colitis." (PMID 34743196, 2021). "Conventionally raised Dok3−/− mice displayed enhanced susceptibility to colitis as evidenced from their greater weight loss and reduced survival compared with WT mice." (PMID 34743196, 2021). "We found that Dok3-knockout (Dok3−/−) mice are highly susceptible to DSS-induced colitis." (PMID 34743196, 2021). "In line with their greater sensitivity to DSS-induced colitis, we saw a loss of protective intestinal bacterial genera such as Bacteriodes in untreated Dok3−/− mice, which correlates with what was observed in the microbiota obtained from IBD patients with elevated fecal levels of S100a8/9." (PMID 34743196, 2021). "The increased expression of S100a8/a9 in Dok3−/− colons during DSS-induced colitis was further validated by reverse transcription-quantitative polymerase chain reaction (RT-qPCR) analysis." (PMID 34743196, 2021). "Hence, we speculate that DOK3 may function in a similar manner to control colitis susceptibility." (PMID 34743196, 2021). "This suggests that immune cells in Dok3−/− colon contributed to S100a8/9 hyper-production, and hence microbial dysbiosis and enhanced inflammation, during colitis." (PMID 34743196, 2021). "Together, these data show that DOK3 protects against DSS-induced acute colitis by limiting colonic inflammation." (PMID 34743196, 2021). "In our study, excessive production of S100a8/9 by neutrophils in Dok3−/− mice consequently promoted microbiome dysbiosis in their gut, resulting in mutant mice succumbing to exacerbated colitis upon DSS treatment." (PMID 34743196, 2021). "In this study, we demonstrated that DOK3 plays a protective role in experimental colitis by restraining JAK2/STAT3 signaling in colonic neutrophils in response to commensal microbes." (PMID 34743196, 2021). "Consequently, upon blockage of S100a8/9 binding to RAGE or TLR4 receptor through administration of FPS-ZM1 or Paquinimod, we were able to rescue colitis severity in Dok3−/− mice, indicating the importance of S100a8/9 in promoting colonic inflammation." (PMID 34743196, 2021). "DOK3-deficiency promotes gut microbial dysbiosis and enhanced colitis susceptibility, which can be reversed by the transfer of normal microbiota from wild-type mice." (PMID 34743196, 2021). "Similarly, treatment with Paquinimod, an inhibitor of S100a9, can also rescue colitis severity of Dok3−/− mice." (PMID 34743196, 2021). "To demonstrate the causal relationship between S100a8/9 levels and the exacerbated colitis phenotype in Dok3−/− mice, we treated WT and Dok3−/− mice with the RAGE antagonist FPS-ZM1, which can inhibit the function of S100a8/9 by blocking their binding to the RAGE receptor." (PMID 34743196, 2021).
colitis (continued). "However, we cannot exclude the possible contribution of RAGE or TLR4 receptor on colitis in Dok3−/− mice, and more work needs to be done in future to address this." (PMID 34743196, 2021). "Here, we showed that Downstream of Kinase 3 (DOK3), an adapter protein involved in immune signaling, confers protection of mice from dextran sodium sulfate (DSS)-induced colitis." (PMID 34743196, 2021). "Hence, to determine if a causal relationship between DOK3 and IBD exists, we induced experimental colitis in wild-type C57BL/6 (WT) and Dok3−/− mice via oral administration of 2% DSS." (PMID 34743196, 2021).
colonic tumors (1 paper, 2022). "However, the rate of invasive colonic tumors in myeloid Gpx4-deficient AOM mice (∼10%) was about 10-fold lower than that in Apc/Dok3 mice (100%)." (PMID 36970719, 2022). "Importantly, marked tumor invasion was also observed in colon tumors in Apc/Dok3 mice; 90% of colorectal tumors in Apc/Dok3 mice, but not in Apc mice, invaded the muscularis propria or beyond." (PMID 36970719, 2022).
colorectal adenocarcinoma (1 paper, 2022). The most common type of colorectal carcinoma. "Also, consistent with the previous observations showing that the invasion front of human colorectal adenocarcinomas displays low proliferative activity, the rate of proliferating Apc/Dok3 tumor cells in the invasion front was significantly lower than that in the tumor center." (PMID 36970719, 2022).
COVID-19 (1 paper, 2022). A disease caused by infection with severe acute respiratory syndrome coronavirus 2. "As S protein from SARS-CoV-2 Delta and Omicron variants can activate TLR4-driven calprotectin production in Dok3-/- neutrophils, our study suggests that targeting calprotectin production may be an effective strategy to combat severe COVID-19 manifestations associated with these emerging variants." (PMID 36172386, 2022). "Recent RNA-seq analysis of neutrophils from COVID-19 patients revealed that Dok3 expression is elevated in severe disease cases, suggesting an association with SARS-CoV-2 infection in humans." (PMID 36172386, 2022). "Blocking of TLR4, JAK2 and STAT3 signaling could prevent excessive production of calprotectin by Dok3-/- neutrophils, revealing new targets for potential COVID-19 therapy." (PMID 36172386, 2022). "Interestingly, RNA-seq analysis of neutrophils from COVID-19 patients revealed that Dok3 expression is elevated in severe disease cases, suggesting a possible role for Dok3 in SARS-CoV-2 infection in humans." (PMID 36172386, 2022).
Crohn disease (1 paper, 2021). A gastrointestinal disorder characterized by chronic inflammation involving all layers of the intestinal wall, noncaseating granulomas affecting the intestinal wall and regional lymph nodes, and transmural fibrosis. "A previous GWAS study of Crohn’s disease and ulcerative colitis implicated a possible role for DOK3 in IBD by virtue of its localization in a susceptibility gene region that also harbors a few other immune-related genes." (PMID 34743196, 2021). "Recently, GWAS studies revealed that Dok3 gene resides within a susceptibility gene region for Crohn’s disease and ulcerative colitis that also harbors many other immune-related genes." (PMID 34743196, 2021). "The possibility that DOK3 might play a role in IBD was first revealed in a GWAS study of Crohn’s disease and ulcerative colitis, but experimental evidence definitively establishing their causal link was lacking." (PMID 34743196, 2021).
dementia (1 paper, 2024). Loss of intellectual abilities interfering with an individual's social and occupational functions. "This study aimed to explore the relationship between aSAH and the increased risk of dementia, emphasizing the roles of DOK3 and PAPOLA as critical genes in this process." (PMID 39726593, 2024). "To investigate the miRNA-mRNA regulatory network involved in aSAH-induced dementia, we focused on DOK3 and PAPOLA as central genes potentially linked to disease progression." (PMID 39726593, 2024). "In this network, DOK3 and PAPOLA, both upregulated, were identified as potential hub genes associated with increased dementia risk post-SAH through apoptotic pathways." (PMID 39726593, 2024). "Additionally, GSEA indicated that upregulation of DOK3 and PAPOLA affected crucial biological pathways potentially linked to processes like immune response modulation and apoptosis, with implications for conditions such as dementia." (PMID 39726593, 2024). "Gene Set Enrichment Analysis (GSEA) suggested that DOK3 and PAPOLA might influence both SAH and dementia through apoptotic pathways, which aligns with literature indicating dysregulated apoptosis in neurodegenerative diseases and neurovascular injury." (PMID 39726593, 2024). "Understanding the molecular dysfunction of DOK3 and PAPOLA in aSAH patients may provide valuable insights into the deregulated molecular pathways that contribute to dementia development, thereby suggesting novel therapeutic targets." (PMID 39726593, 2024). "The classification performance of seven core DEGs identified in SAH and dementia was evaluated, with ROC curve analysis demonstrating their strong discriminative capabilities, particularly PAPOLA in dementia with an AUC of up to 0.989, followed by DOK3, LONRF3, and MILR1, all exceeding 0.900." (PMID 39726593, 2024).
Immunodeficiency (1 paper, 2021). Failure of the immune system to protect the body adequately from infection, due to the absence or insufficiency of some component process or substance. "DOK3 interacts with LCK, the respective LCK deficiency is characterized by several phenotypes (diarrhea, immunodeficiency, T-cell lymphopenia) closely related to those of our patient." (PMID 33893283, 2021).
intestinal benign tumor (1 paper, 2022). "In the current study, we show that Dok-3 deficiency induces malignant progression in the intestinal benign tumor model, Apc mice." (PMID 36970719, 2022). "Here, we found that disruption of the Dok-3 tumor suppressor gene led to malignant progression in the intestinal benign tumor model ApcMin/+ mice." (PMID 36970719, 2022).
intestinal tumors (1 paper, 2022). "In the current study, by using ApcMin/+ mice lacking Dok-1/-2 or Dok-3, we show that Dok-1/-2 and Dok-3 play distinctive roles in growth and malignant progression of intestinal tumors." (PMID 36970719, 2022).
neuropathic pain (1 paper, 2020). Chronic pain caused by damage to nerve fibers. "In the present study, we determined the role of DOK3 in activating microglia-induced neuropathic pain and investigated the underlying mechanisms associated with GPR84." (PMID 33281117, 2020).
osteoporosis (1 paper, 2021). A condition of reduced bone mass, with decreased cortical thickness and a decrease in the number and size of the trabeculae of cancellous bone (but normal chemical composition), resulting in increased fracture incidence. "Our study reveals a novel ULK1/DOK3/Syk axis that regulates OC differentiation, and targeting ULK1 is a potential therapeutic strategy for osteoporosis." (PMID 34820053, 2021). "Therefore, our study reveals a novel ULK1/DOK3/Syk axis that regulates osteoclast differentiation and bone resorption, and targeting ULK1 is a potential therapeutic strategy for osteoporosis." (PMID 34820053, 2021).
Pain (1 paper, 2020). An unpleasant sensory and emotional experience associated with actual or potential tissue damage, or described in terms of such damage. "In the present study, we broadened the potential application of pregabalin in the improvement of upregulated DOK3-induced neuropathic pain in mice." (PMID 33281117, 2020).